LAMA4 (laminin subunit alpha 4)
Diseases named in the same sentence as LAMA4 in open-access papers (continued):
Sharing a sentence is not in itself a finding about the gene and the disease.
tumor (continued). "LAMA4 was upregulated in GC tissues, and high levels of LAMA4 expression were significantly correlated with tumor invasion." (PMID 34414238, 2021). "After adjustment for tumor purity, we found a significant correlation between LAMA4 expression and markers of M2 macrophages and TAMs." (PMID 34414238, 2021). "In the present study, evaluation of the differential expression in GC revealed that LAMA4 was highly expressed in tumor samples." (PMID 34414238, 2021). "In GC cells, LAMA4 knockdown led to a reduced tumor invasive capability via inhibiting the expression of MMP2, a critical enzyme that degrades ECM." (PMID 34414238, 2021). "LAMA4 was shown to be specifically upregulated in hepatocellular carcinoma and was significantly correlated with tumor invasion and metastasis." (PMID 34414238, 2021). "Liver-metastatic tumor tissues showed higher LAMA4 expression compared to paired primary tumor tissues." (PMID 32929348, 2020). "We next investigated the expression of mature PDPN and LAMA4 transcripts in tumor tissue and normal spleen using RT-PCR." (PMID 32571313, 2020). "LAMA4 protein expression and distribution highly coincide with CAFs on mice liver-metastatic tumor tissues determined by serial IHC staining (α-SMA positive areas did not express the blood vessel marker CD31)." (PMID 32929348, 2020). "Again, as with PDPN, anti-LAMA4 staining was also observed in the cytoplasm in the endothelial cells from tumor-adjacent blood vessels." (PMID 32571313, 2020). "LAMA4, which encodes a secreted ECM protein, is found to promote tumor re-initiation in multiple organ microenvironments." (PMID 32332873, 2020). "For this analysis we focused on PDPN (FDR 6.43E-05, fold change 3.62) and LAMA4 (FDR 1.58E-09, fold change 3.77) because these molecules have been previously associated with cancer progression in other tumor types." (PMID 32571313, 2020). "Anti-LAMA4 staining was strong in extracellular regions of the tumor and in endothelial cells lining blood vessels." (PMID 32571313, 2020). "Given the previously defined roles for LAMA4 in cancer progression and tumor metastasis, our findings raise the possibility that LAMA4 is an important mediator of canine HSA pathobiology." (PMID 32571313, 2020). "Taken together, these published studies indicate that LAMA4 plays a key role for vascular development, tumor progression and metastasis." (PMID 32571313, 2020). "Meanwhile, we observed a positive correlation between LAMA4 relative expression and tumor histologic grade in patient samples." (PMID 32929348, 2020). "LAMA4 high expression tumor tissue was accompanied by a high level of CAFs, whereas LAMA4 low expression patient samples showed a significantly low level of CAFs." (PMID 32929348, 2020). "LAMA4 mRNA in tumor tissues and cell lines was 50% lower than that in healthy tissues and cell lines." (PMID 32489317, 2020). "Next, we performed IHC analysis of PDPN and LAMA4 on HSA tumor sections to confirm that these molecules are expressed in tumor tissue at the protein level and to investigate their localization." (PMID 32571313, 2020). "Distributions of LAMA4 protein and CAFs were examined by serial IHC staining in liver metastatic tumor tissues in nude mice." (PMID 32929348, 2020). "As far as the tumor grade was concerned, a significant alteration among the different histological grades was observed only for LAMA4, with a remarkable decrease of its expression levels passing from G2 to G3 ccRCC." (PMID 24194935, 2013). "Among the genes represented in the Met library, many are associated to tumor growth, invasiveness and metastasis, such as TM4SF1, LAMA4, G3BP2, CD59 antigen, and SPP1." (PMID 18211678, 2008). "Previous studies showed that LAMA4 could affect tumour cell behaviour by promoting migration and invasion, and induce tumour progression by regulating the composition and structure of the ECM." (PMID 40375605, 2025).
tumor (continued). "The higher the expression of LAMA4 in HCC, the poorer the prognosis of patients, suggesting that LAMA4[circle112550019-112550510] derived from LAMA4 may have a similar impact and could serve as a novel tumor marker for predicting future cancer occurrence." (PMID 39850493, 2024). "In fact, we were able to detect five upregulated proteins in the normal mucosa adjacent to the tumor, namely laminin subunit alpha-4 (LAMA4), elastin microfibril interfacer 1 (EMILIN1), LTBP1 and fibrinogen beta chain (FGB), as well as proteoglycan versican core protein (VCAN)." (PMID 35340765, 2022). "LAMA4 knockdown in metastatic tumor tissues on liver was validated by IHC staining." (PMID 32929348, 2020). "IHC staining was performed to evaluate LAMA4 protein expression in tumor tissues." (PMID 32929348, 2020). "LAMA4 knockdown in metastatic tumor tissues on liver was confirmed." (PMID 32929348, 2020). "In addition to collagen, we also found that PDPN and LAMA4 were highly overexpressed in HSA tumor tissue when compared to normal tissue." (PMID 32571313, 2020). "Additionally, we further characterize two ECM-associated molecules that were highly overexpressed in HSA tumor tissue, podoplanin (PDPN) and laminin alpha 4 (LAMA4)." (PMID 32571313, 2020). "Anti-PDPN and LAMA4 staining appeared to be primarily cytosolic in tumor cells from this sample." (PMID 32571313, 2020). "Moreover, preliminary data point that negative correlation of expression levels for genes SORCS2 and LAMA4 is a phenomenon which is, indeed, specific to only this tumor type." (PMID 31781574, 2019). "LAMA4 plays an important role in tumor progression and may be an important target in treatment of TNBC." (PMID 29434522, 2018). "We found that LAMA4+ cells were barely detectable in NT kidney and their expression was limited to the small and medium renal artery walls, while we observed a significant increase (p < 0.005) of LAMA4 in ccRCC tumor tissue, with a distribution similar to the peritubular capillary network." (PMID 24194935, 2013). "LAMA4 and LAMB1 might be associated with tumor purity in OC." (PMID 34512203, 2021). "Finally, the relationship between LAMA4 expression and tumor immune infiltration was investigated." (PMID 34414238, 2021). "Additionally, laminin encoded by LAMA4, LAMB1, and LAMB2 mediate adhesion through Integrin binding—specifically the Integrin α6β4, composed of integrin α6 (ITGA6) and Integrin β4 (ITGB4)—is suggested to be essential for tumor development and progression, promoting pro-cancer signaling pathways." (PMID 40333631, 2025). "LAMA4, through its binding to integrins, phosphorylates FAK and activates AKT, inhibiting pro-apoptotic proteins, This mechanism enables tumor cells to resist anoikis and metastasize." (PMID 40612108, 2025). "We found that the promoting effects of LINC00629 on tumour development and lung metastasis were abolished by KLF4 or LAMA4 depletion in nude mice." (PMID 36539799, 2022). "Among the NAC-induced miRNAs in non-responders is miR-539-5p, which has been shown to act as a tumor suppressor in BC by targeting EGFR, LAMA4, and SP1 thus leading to the inhibition of proliferation and migration of BC cells." (PMID 36387168, 2022). "Both LAMA4-depleted SUIT-2 and AsPC-1 cells showed decreased capability of tumor formation in liver compared with WT SUIT-2 and AsPC-1 cells." (PMID 32929348, 2020). "LAMA4 protein expression and CAFs (α-SMA) were semi-quantitatively scored according to IHC staining intensity in liver-metastatic tumor tissues." (PMID 32929348, 2020). "Those genes reportedly involved in tumor cell adhesion, gap junction and ECM, such as CHD1, Cx26, Cx43, Cx45, COL1A1, FN1, LOX, ITGB1 and LAMA4, were also up-regulated following 3D cultures." (PMID 26055407, 2015). "In OC cells, MEG3 could inhibit tumor cells migration and invasion potentials by sponging up miR-219a-5p and miR-30e-3p, resulting in the downregulation of EGFR and increase in laminin subunit alpha 4 (LAMA4), respectively." (PMID 36551518, 2022).
tumor (continued). "The localization pattern of anti-LAMA4 staining was similar to that of PDPN, with little staining being seen in normal splenic tissue and strong anti-LAMA4 staining being observed in the cytoplasm of HSA tumor cells encircling collagen fibrils." (PMID 32571313, 2020). "There were negative correlations between OC tumor purity and LAMA4 and LAMB1." (PMID 34512203, 2021). "Substantial differences between tumor and neighboring healthy cortex were found in both interstitial matrix proteins, such as collagen 6 (COL6A1, COL6A2, COL6A3), and basement membrane components such as collagen 4 (COL4A1, COL4A2) and laminins (LAMA5, LAMA4, LAMB1, LAMB2, LAMC1)." (PMID 34884982, 2021). "Moreover, based on the lack of significantly increased expression of COL5A2 and LAMA4 genes in in vitro tumor cells after TGFβ or β-estradiol treatment, we speculate that signals other than TGFβ or β-estradiol contribute in regulating ECM3 genes." (PMID 23441215, 2013). "Results show that, while PDPN or LAMA4 transcripts were either absent or weakly expressed in normal spleen, LAMA4 was significantly expressed in all three tested HSA tumor samples while PDPN was robustly expressed in one (C356) of the three HSA samples." (PMID 32571313, 2020).
cancer (37 papers, 2009 to 2025). A tumor composed of atypical neoplastic, often pleomorphic cells that invade other tissues. "LAMA4 expression was found to be increased in breast cancer cells and associated with cancer initiation and progression." (PMID 34414238, 2021). "LAMA4 is a cancer-associated gene and a very promising malignant tumor therapeutic target." (PMID 37694778, 2024). "Therefore, it can be hypothesized that low expression of LAMA4 in EC is associated with lesser maturation of endothelia in cancer neoangiogenesis." (PMID 37612452, 2023). "Our forthcoming studies will engage both in vitro and in vivo models to authenticate the influence of LAMA4 on pivotal signaling pathways, as well as its contribution to cancer development and response to therapy." (PMID 40881886, 2025). "Increasing evidence indicates that LAMA4 plays a significant role in promoting survival, proliferation and migration in several cancers." (PMID 36539799, 2022). "Several upregulated genes (LRP1, SERPINA1, HRG, ILK, CAV1, and LAMA4) identified in our study are involved in GEM resistance in human cancer 23-28." (PMID 35281857, 2022). "Subsequently, we showed that Lama4 and Lama5 expression dynamically react to diverse immune and tolerance influences, including cancer, gut microbiota, and allotransplantation in mice." (PMID 35775481, 2022). "LAMA4, known as a basement membrane glycoprotein, promotes the migration, proliferation, and survival of endothelial, blood, and cancer cells." (PMID 34414238, 2021). "LAMB3 and LAMA4 belong to the laminin subunit family and have been reported to be involved in the metastasis and invasion of some types of cancer." (PMID 34456632, 2021). "In recent years, some researchers paid close attention to this gene and explored the effect of LAMA4 on cancers." (PMID 32489317, 2020). "Specific downregulation of cancer cell-derived secreted LAMA4 inhibited the viability and migration of CAFs." (PMID 32929348, 2020). "Several studies found that the abnormal expression of LAMA4 was related to the formation and function of the endothelium, including the cell migration and invasion of certain types of cancers in vivo and in vitro." (PMID 32489317, 2020). "LAMA4 belongs to the laminin family and plays an important role in many cancers." (PMID 36539799, 2022). "Over recent decades, the effects of LAMA4 on cancers have attracted wide attention." (PMID 34414238, 2021). "Moreover, knockdown of LAMA4 inhibits proliferation, migration and invasion of these cancer cells in vitro." (PMID 31781574, 2019). "Other studies have also shown that PTGDS, GREM1, LAMA4, S100A14, PREX2, and GLS2 have potential value in promoting cancer progression and predicting cancer prognosis." (PMID 37306872, 2023). "On the other hand, miR-200b is an onco-suppressor factor that inhibits downstream targets such as laminin subunit alpha 4 (LAMA4) to reduce the invasion and proliferation of cancer cells." (PMID 32380783, 2020). "The qPCR studies identified five mRNA (CA11, MEDAG, LAMA4, SPINT2, NANOG) and six miRNA (let-7b, miR23b, miR29a, miR30d, miR205, miR720) that were significantly differentially expressed between cancer ascites and peritoneal fluids." (PMID 29499737, 2018). "This is the first account of osteonectin (SPARC; Vesiclepedia ID, VP_6678) and laminin subunit alpha-4 (LAMA4, VP_3910) proteins in cancer EVs, although corresponding mRNA species were documented in GBM EVs." (PMID 27770278, 2017). "Meanwhile, other cell-cell adhesion-related molecules, such as laminins (LAMA4, LAMA5, LAMB1, LAMB2 and LAMC2) and integrins (ITGA5, ITGA5, ITGB5, ITGA11 and ITGBL1), are elevated in cancer tissues." (PMID 22905095, 2012).
cancer (continued). "Interestingly, elevated levels of LAMA4 and LAMC1 are observed in cancer cells, which suggests that their upregulation in SIRT1-depleted adipocytes reflects their hyperplastic phenotype." (PMID 33854178, 2021). "Interestingly, genes that have been previously found to be overexpressed in other cancers such as hepatocyte growth factor (HGF), laminin alpha 4 (LAMA4) and androgen receptor (AR) were also found to be more highly expressed in MEi cells compared to BM-MSCs." (PMID 25229469, 2014). "It implies that LAMA4 may exert its pro-tumorigenic effects through a two-pronged mechanism: externally, by contributing to the structural and signaling landscape of the remodeled ECM, and internally, by directly influencing gene expression programs within the cancer cell nucleus." (PMID 40881886, 2025). "In contrast, DEGs with lower expression in patient relative to healthy control fibroblasts were enriched for one KEGG category ('Pathways in Cancer' as represented by the SMAD3, LAMA4, PML and DAPK1 genes), but no GO categories." (PMID 23036268, 2012).
infection (2 papers, 2014 to 2018). The state of being infected such as from the introduction of a foreign agent such as serum, vaccine, antigenic substance or organism. "In this study, the gene expression of the identified zebrafish laminin, alpha 4 (Lama4), declined as infection advanced, indicating that vascular integrity may not be maintained." (PMID 24757665, 2014).
neuromuscular disease (1 paper, 2019). "LAMA4 is implicated in neuromuscular diseases, and LAMA4 mutations have been reported in DCM and HCM patients." (PMID 30650640, 2019).
LAMA4 also shares sentences with these, for which no sentence is quoted: cardiac hypertrophy (2 papers); deafness (2); endothelial dysfunction (2); Arrhythmia (1); asthma (1); atrial fibrillation (1); atrial standstill (1); Autoimmunity (1); bipolar disorder (1); bladder cancer (1); brain tumor (1); cardiovascular diseases (1); cattle disease (1); cervical cancer (1); childhood asthma (1); chordoma (1); colitis (1); complication (1); Congenital muscular dystrophy type 1A (1); coronary artery disease (1); diabetes (1); diabetic nephropathy (1); diabetic retinopathy (1); digestive system neoplasm (1); dyslipidemia (1); endometriosis (1); epidermolysis bullosa (1); genetic disorders (1); glaucoma (1); head and neck cancer (1).
A further 28 diseases each share a sentence with LAMA4 in 1 paper.